TEKT1 (tektin 1)
Description:
Microtubule inner protein (MIP) part of the dynein-decorated doublet microtubules (DMTs) in cilia and flagellar axoneme. Forms filamentous polymers in the walls of ciliary and flagellar microtubules.
Tractability: Small molecule: a structure with a bound ligand is known. PROTAC: UniProt records ubiquitination sites on it; ubiquitination databases record sites on it.
Target class: Structural protein
Gene: Protein-coding gene on chromosome 17 (6,789,133 to 6,831,761, reverse strand). Ensembl gene ENSG00000167858.
Subcellular location: Cytoplasm, cytoskeleton, cilium axoneme; Cytoplasm, cytoskeleton, flagellum axoneme
Gene Ontology:
Molecular function: protein binding
Biological process: cilium assembly; cilium movement involved in cell motility; flagellated sperm motility
Cellular component: axonemal microtubule; nucleus; axonemal A tubule inner sheath; microtubule cytoskeleton; sperm flagellum; axoneme; cilium; cytoplasm
Genetic constraint (gnomAD): Loss-of-function variants: 37 observed, 41.14 expected, observed/expected ratio (o/e) 0.9, 90% interval 0.69 to 1.18. The upper end of that interval is the gene's LOEUF score, 1.18, which puts it in group 5 of 6, group 1 being the genes least tolerant of losing a copy. Missense variants: 492 observed, 541.24 expected, observed/expected ratio (o/e) 0.91, 90% interval 0.84 to 0.98. Synonymous variants: 207 observed, 210.39 expected, observed/expected ratio (o/e) 0.98, 90% interval 0.88 to 1.1.
Gene-disease validity (ClinGen):
ClinGen rates the evidence that TEKT1 causes each of these diseases.
primary ciliary dyskinesia (autosomal recessive): Disputed. A rare, genetically heterogeneous, primarily respiratory disorder characterized by chronic upper and lower respiratory tract disease.
Homologues: Orthologues: chimpanzee TEKT1 (99% identical), macaque TEKT1 (97% identical), pig TEKT1 (89% identical), guinea pig TEKT1 (85% identical), rabbit TEKT1 (84% identical), dog TEKT1 (84% identical), rat Tekt1 (83% identical), mouse Tekt1 (83% identical), tropical clawed frog tekt1 (66% identical), zebrafish tekt1 (46% identical), Drosophila melanogaster Tektin-C (30% identical). Paralogues in human: TEKT4 (38% identical), TEKT3 (35% identical), TEKT5 (35% identical), TEKT2 (33% identical), MAFIP (12% identical).
Diseases named in the same sentence as TEKT1 in open-access papers:
TEKT1 is named in the same sentence as 13 diseases in open-access papers, as found by Europe PMC text mining. Sharing a sentence is not in itself a finding about the gene and the disease. The quoted sentences say what the papers report.
asthenozoospermia (4 papers, 2020 to 2026). "Phenotypic comparisons between Tekt1 and Tssk6 KO mice suggest their involvement in distinct subtypes of asthenozoospermia." (PMID 41764189, 2026).
ciliopathy (3 papers, 2019 to 2025). A genetic disorder of the cellular cilia or the cilia anchoring structures, the basal bodies, or of ciliary function. "When Tekt1 expression is knocked down, zebrafish presented very mild body curvature, a classical ciliopathy-associated phenotype thought to be linked to convergence–extension defects." (PMID 39949046, 2025). "A translation-blocking morpholino for Tekt1 resulted in the loss of Tekt1 and a ciliopathy phenotype with situs inversus and cysts in the pronephros." (PMID 39949046, 2025).
Infertility (2 papers, 2013 to 2025). "Loss of Tekt1–5 causes microtubule instability, impaired motility, and diseases like infertility, retinal degeneration, Mainzer-Saldino syndrome, and diabetic nephropathy." (PMID 39949046, 2025). "We found copy number differences in infertile dogs compared with fertile for genomic regions encompassing TEKT1, DNM2 and SOX8 genes, suggesting a role in infertility biology if deleted or duplicated with respect to reference copy number." (PMID 24373333, 2013).
male infertility (2 papers, 2021 to 2026). The inability of the male to effect fertilization of an ovum after a specified period of unprotected intercourse. "The proper organization of the centrosome of sperm, in the function of the sperm transcriptome tektin-1 (TEKT1) is essential for oocyte genome activation leading to successful fertilization, and any defects in this process might lead to male infertility." (PMID 33902175, 2021).
infection (2 papers, 2023 to 2024). The state of being infected such as from the introduction of a foreign agent such as serum, vaccine, antigenic substance or organism. "Cells were allowed to differentiate for 14 to 21 days prior to infection, and differentiation was confirmed by the endpoint PCR of differentiation markers MUC5AC, CBE1, SCGB1A1, BPIFA1 and TEKT1." (PMID 39772226, 2024).
TEKT1 also shares sentences with these, for which no sentence is quoted: breast carcinoma (1 paper); cancer (1); diabetic nephropathy (1); leprosy (1); Mainzer-Saldino syndrome (1); retinal degeneration (1); situs inversus (1); tumor (1).